EPCAM (epithelial cell adhesion molecule)
Diseases named in the same sentence as EPCAM in open-access papers (continued):
Sharing a sentence is not in itself a finding about the gene and the disease.
pancreatic cancer (159 papers, 2008 to 2025). "An EpCAM-binding variant of inRas37 for treatment of pancreatic cancers was developed by simply swapping the integrin-binding peptide with an EpCAM-recognizing cyclic peptide." (PMID 38282957, 2024). "For PANC-1, we assessed CD24, CD44, and EpCam since these have been linked with a more specific phenotype for CSCs in pancreas cancer." (PMID 38542325, 2024). "Given that pancreatic cancer is associated with a low PD-L1 expression, a similar phenotype was observed in EpCAM+ cancer cells." (PMID 36293034, 2022). "In pancreatic cancer, detection of CTCs with mesenchymal markers and minimal EpCAM expression portended a worse prognosis and was associated with higher stage tumors and metastatic disease." (PMID 34209658, 2021). "Large extracellular vesicles, specifically AnnexinV+ EpCAM+ CD147+ tumor-associated microparticles were reported to facilitate the detection of pancreas carcinoma." (PMID 32974169, 2020). "Higher expression of EPCAM is associated with an improved outcome in pancreatic cancer by suppressing cell activity." (PMID 29515771, 2018). "Additionally, MLH1 was positively associated with ANKRD55 expression, while EPCAM was negatively associated with ANKRD55 expression in pancreatic cancer." (PMID 33827590, 2021). "In the present work, we have used the γ-secretase inhibitor IX (GSI) to show that the Notch signalling pathway contributes to the acquisition of epithelial mesenchymal transition (EMT) and is associated with the maintenance of pancreatic tumor initiating CD44+/EpCAM+ cells." (PMID 23094026, 2012). "High EpCAM expression was associated with poor survival rates for breast, gall bladder and squamous cell carcinoma of the esophagus whereas better survival rates were reported for renal cell carcinoma and pancreatic cancer." (PMID 22590529, 2012). "We further established the pancreatic tumor spheroids model and investigated the killing efficiency of EpCAM CAR-T cells in three-dimensional culture systems." (PMID 41417221, 2025). "In this study, we comprehensively evaluate the preclinical efficacy in vitro and in vivo of EpCAM CAR-T cells in pancreatic cancer." (PMID 41417221, 2025). "This approach enabled the detection of the expression of two pancreatic cancer biomarkers, live erythropoietin-producing hepatocellular A 2 (EphA2), and epithelial cell adhesion molecule (EpCAM)." (PMID 40284444, 2025). "Immunocompromised NSG-MHC I/II DKO mice were inoculated with B7-H3+ EpCAM+ HPAF-II human pancreatic cancer xenografts, engrafted with human PBMCs following the formation of palpable tumors, and then dosed weekly with antibodies." (PMID 39301613, 2025). "These preclinical results provided evidence of the efficacy and feasibility of EpCAM CAR-T cells for the immunotherapy of pancreatic cancer." (PMID 41417221, 2025). "Then, we tested the anti-tumor efficacy and safety of EpCAM CAR-T cells in another highly invasive xenograft model of pancreatic cancer." (PMID 41417221, 2025). "These preclinical investigations demonstrated the anti-tumor efficacy and feasibility of two second-generation EpCAM CAR-T cells against pancreatic cancer." (PMID 41417221, 2025). "Pancreatic cancer stem cells (PaCSCs) are maintained by specific surface markers (CD44, CD133, EpCAM, ALDH1A1) and regulated by stemness-associated signaling pathways such as Wnt/β-catenin, Notch, Hedgehog, and TGF-β." (PMID 40881675, 2025). "Our preclinical results provided evidence of the efficacy and feasibility of EpCAM CAR-T cells for the immunotherapy of pancreatic cancer." (PMID 41417221, 2025). "Effectiveness was measured with analysis of overall survival, disease-free survival, distant recurrence, locoregional recurrence, and measuring of pancreatic cancer stem cells (EpCAM+CXCR4+CD133+)." (PMID 38730669, 2024).
pancreatic cancer (continued). "Although the EpCAM BiTE was tested on pancreatic cancer cells and CSCs at a preclinical level with encouraging results, Phase I clinical studies did not include PaCa patients." (PMID 39759138, 2024). "Epithelial cell adhesion molecule (EpCAM) is commonly upregulated and functionally altered in pancreatic cancer cells, including CSCs." (PMID 39759138, 2024). "For cancer-derived EVs, epithelial cell surface molecules including EPCAM were effective markers of pancreatic cancer, while endothelial cell-derived EVs with CD31 and CD146 represented atherosclerotic disease markers." (PMID 38436899, 2024). "EpCAM from pancreatic cancer cells was specifically captured using CKAAKN (a peptide specific to pancreatic cancer cells)." (PMID 39639411, 2024). "Solidomab treatment was found to effectively eradicated EpCAM+CSCs, originating from colon or pancreatic cancer patients that were inoculated into NOD/SCID mice." (PMID 38140103, 2023). "Despite the fact that 96% of pancreatic cancers are EpCAM-positive, EpCAM expression levels vary, with only half the tumors exhibiting strong expression." (PMID 38044994, 2023). "Studies have shown that vimentin antibodies are more effective for isolating CTCs from certain cancers, such as breast and pancreatic cancer, than EpCAM antibodies alone." (PMID 37345161, 2023). "In this paper, we evaluated the efficacy of isolating CTCs from the blood of patients with prostate and pancreatic cancer using EpCAM (an epithelial marker) and vimentin (a mesenchymal marker) antibodies individually and in combination." (PMID 37345161, 2023). "It is reported that CSV can be used as a target for capturing mesenchymal CTCs, and the rate of CTC detection by the CSV antibody is higher than that by the EpCAM antibody in breast and pancreatic cancer patients." (PMID 37914786, 2023). "In conclusion, CD8+ T cells responding to WT1 or SMAD4P130L neoantigen expressed in EpCAM+ pancreatic cancer cells were detected in MPE." (PMID 36293034, 2022). "This is important for studying pancreatic cancer as the commonly used isolation marker, epithelial cell adhesion molecule (EpCAM), has varying expression levels in pancreatic cancer." (PMID 35887203, 2022). "GPC-1 combined with EpCAM has been found to differentiate sEVs derived from pancreatic cancer or normal pancreatic epithelial cells with 90% accuracy." (PMID 36167539, 2022). "The primary objective of the study is to characterize alternate surface biomarkers to EpCAM on CTCs that express low or negligible levels of surface EpCAM in pancreatic cancer patients." (PMID 36009530, 2022). "More importantly, dichloroacetate inhibited the formation and viability of EpCAM+ pancreatic cancer cells." (PMID 36369033, 2022). "p-21 activated kinase 4 (PAK4) was found to enhance stem cell-like characteristics through STAT3 signaling and increase the expression of EpCAM in pancreatic cancer cells." (PMID 36369033, 2022). "CD8+ T cells responding to WT1 or SMAD4P130L neoantigen expressed in very few EpCAM+ pancreatic cancer cells were detected in MPE." (PMID 36293034, 2022). "It has been demonstrated that EpCAM is a reliable marker for the identification of CSCs in various tumor types including pancreatic cancer." (PMID 35391557, 2022). "We isolated cancer stem cells (CSCs) from the human PANC-1 pancreatic cancer cell line as CD44+CD24+EpCAM+ cells." (PMID 34885233, 2021). "Another study addressed the same issue using CAPAN-1 pancreatic cancer cells spiked into 108 peripheral blood mononucleated cells and also found a considerable reduction in recovery upon staining after EpCAM-based capture." (PMID 34884994, 2021). "In HEK293 and rat pancreatic cancer cell lines, EpCAM and claudin-7 were shown to form a complex which promoted migration and tumor growth, and this was associated with increased ERK signaling." (PMID 34209658, 2021).
pancreatic cancer (continued). "Previous study has shown CTC detection rate with CSV antibody was higher than that with EpCAM antibody in breast and pancreatic cancers." (PMID 34055642, 2021). "As a result, ductal (CA2, CK19, and SOX9)/pancreatic cancer (EpCAM and CD44) markers decreased and acinar markers (SYP and PTF1A) increased by inhibitor treatment in KiPCs." (PMID 33233448, 2020). "Compared with PCs and iPCs, the gene expression levels of some pancreatic cancer markers (epithelial cell adhesion molecule (EpCAM), CD44, CD133, and c-MET) were significantly increased in KiPCs." (PMID 33233448, 2020). "We have found that indirect iodination using PIB was the most optimal labeling strategy that enabled high contrast imaging of EpCAM expression in pancreatic cancer in vivo." (PMID 32392820, 2020). "Recently, we have demonstrated that imaging of EpCAM expression in pancreatic cancer xenografts using radiolabeled DARPin Ec1 is feasible." (PMID 32392820, 2020). "To analyze the suitability of model cells for enrichment experiments, we investigated three different human pancreatic cancer cell lines for their EpCAM and MUC-1 surface expression." (PMID 32290064, 2020). "Both the mesenchymal marker vimentin and the epithelial marker EpCAM are known to be overexpressed in most pancreatic carcinomas." (PMID 31963309, 2020). "FF-nPES assay results indicate that FF-nPES analysis of EV EpCAM levels in serial mouse serum samples can both detect the development of early pancreatic tumors and evaluate their progression." (PMID 31921310, 2019). "This represents a useful prognostic factor and also suggests that future treatment modalities who target EpCAM should be tested in pancreatic cancer patients selected by exosome EpCAM expression." (PMID 31048929, 2019). "Adherent cells isolated from PDOX varied in shape and size and strongly expressed EpCAM, as well as showing greater tumor growth potential than the commercially available pancreatic cancer cell line CFPAC-1." (PMID 31572675, 2019). "In metastatic lymph nodes from lung, breast and pancreas cancers, the upregulation of Ets family transcription factor Esx/Elf3 in metastatic lymph nodes correlated well with expression of EpCAM." (PMID 31225512, 2019). "More recently, EpCAM was also detected in exosomes fraction after surface protein exosomal profiling in plasma from pancreatic cancer patients." (PMID 31225512, 2019). "FF-nPES detected a serum EV EpCAM concentration change corresponding to the initial development of a spontaneous pancreatic tumor." (PMID 31921310, 2019). "EV EpCAM levels in the blood samples of the KPC mouse were found to significantly increase (p-value = 0.0013) at the first time point at which a pancreatic tumor mass was detectable." (PMID 31921310, 2019). "The EpCAM−, CK+, CD45− cells captured by rVAR2 were confirmed to be genuine CTCs by KRAS mutation analysis on single cells from pancreatic cancer patient blood samples." (PMID 30115931, 2018). "Kaplan-Meier analysis showed that the expression of EPCAM was inversely correlated to the survival (months) of pancreatic cancer." (PMID 29515771, 2018). "The rVAR2-based CTC isolation method showed markedly increased CTC retrieval compared to EpCAM-based techniques when testing blood from prostate, lung, and pancreatic cancer patients." (PMID 30115931, 2018). "Similar cytotoxic effects were observed among all three pancreatic cancer cell lines using a positive control ADC targeting epithelial cell adhesion molecule (EpCAM)." (PMID 29507667, 2018). "rVAR2-isolated cells from two of the pancreatic cancer blood samples were stained for EpCAM in addition to the routine CK and CD45 used for detection." (PMID 30115931, 2018).
pancreatic cancer (continued). "α-Amanitin was tested in preclinical studies on pancreatic carcinomas and epithelial cell adhesion molecule (EpCAM)-expressing malignancies mouse models." (PMID 30029518, 2018). "We compared an EpCAM-dependent (IsoFlux) and a size-dependent (automated Siemens Healthineers filtration device) isolation method for the enrichment of pancreatic cancer CTCs." (PMID 29156783, 2017). "We used an EpCAM-dependent immune-affinity approach and a filtration method to examine if the variable EpCAM expression in pancreatic cancer cells has an impact on the recovery rate." (PMID 29156783, 2017). "Although most pancreatic tumors are EpCAM-positive (96%), the expression levels of EpCAM are heterogenous with only half of the tumors showing strong expression." (PMID 29156783, 2017). "Especially in pancreatic cancer, isolation based only on EpCAM expression has produced very diverse results." (PMID 29156783, 2017). "In this study, the EpCAM was chosen because it is highly expressed by pancreatic cancer and has a critical role in acute inflammation." (PMID 27886058, 2016). "Markers for prospectively identifying pancreatic cancer stem cells are CD44+CD24+EpCAM+, CD133+, and ALDH+." (PMID 26673007, 2016). "In the pancreatic cancer cells L3.6pl contained 59.1% CD24+/CD44+ cells of which 94.9% were EpCAM+/CD166+, yielding a 56.1% CSC subset." (PMID 27512958, 2016). "CSC populations at basal level were detected in PANC-1 cells using multi-fluorescence labeled flow cytometry to identify CD24+CD44+EpCAM+ cells, as these cellular surface markers were indicative for pancreatic cancer stem cells." (PMID 27764163, 2016). "We have shown that cultured cells originating from a pancreatic tumor are successfully identified by the system; however these are adherent cultured cells and thus are likely to express EpCAM at high levels." (PMID 26498594, 2015). "Recent studies in other human cancers reported loss of membranous expression of the intracellular domain of EpCAM to be a frequent event and predicted poor survival in patients with pancreatic cancer and gastric cancer." (PMID 25695234, 2015). "Our flow cytometric analyses of resected pancreatic cancer tissues revealed that the percentage of CD166+ cells ranged from 33.8 to 70.2% among EpCAM+ cells, suggesting that CD166 expression was frequent in pancreatic cancers." (PMID 25221999, 2014). "In pancreatic cancer the Src homology region 2 domain-containing tyrosine phosphatase 1 (SHP-1) is able to de-phosphorylate the epithelial cell adhesion molecule E-cadherin, thereby stabilizing inter-epithelial cell junctions in a SSTR2-dependent fashion." (PMID 25010045, 2014). "Anti-EpCAM MBs efficiently (>77%) isolated rare mouse breast 4T1, human prostate PC-3 and pancreatic cancer BxPC-3 cells spiked into 1, 3 and 7 ml (respectively) of plasma-depleted blood." (PMID 23516425, 2013). "EPCAM overexpression correlated with shorter overall survival among patients with ampullary cancer and advanced stage pancreatic cancer, and was found to correlate with tumor stage of ampullary cancer." (PMID 24422715, 2013). "There was no cross-platform correlation in CTC number consistent with their detection of different subsets of CTCs suggested by the heterogeneity of EpCAM and CK expression in both pancreatic cancer patients’ CTCs and tumours and consistent with EMT." (PMID 22187035, 2012). "Pancreatic tumour specimens were available for 2 of 3 patients presenting with CTM: patient 50 had a poorly differentiated EpCAM (3+)-positive carcinoma, with CK-positive cells within CTM by ISET." (PMID 22187035, 2012). "To extend our assessment of EMT during metastasis, we compared the expression of EMT markers (EpCAM, CKs, E-Cadherin and Vimentin) in pancreatic tumours and in pancreatic CTCs." (PMID 22187035, 2012).